BCL2 (BCL2 apoptosis regulator)
Diseases named in the same sentence as BCL2 in open-access papers (continued):
Sharing a sentence is not in itself a finding about the gene and the disease.
diabetes (continued). "Both immunohistochemistry and RT-qPCR analyses revealed that CAR therapy mitigated the diabetes-induced elevation in Bax and reduction in Bcl-2 expression." (PMID 41516168, 2025). "In this study, STZ-induced diabetes in rats resulted in higher expression of apoptotic markers like Bax and caspase 3, along with a reduction in BCL-2 expression in liver tissues." (PMID 40765566, 2025). "Taken together, these findings emphasize the intertwined relationship between Bcl-2 and Bcl-xL protein expression and the pathophysiology of diabetes." (PMID 39857806, 2025). "The therapeutic potential of Bcl-2/Bcl-xL inhibitors in diabetes emerged in 2019, when two complementary studies introduced the use of BH3 mimetics as senolytic compounds, which are drugs that selectively induce apoptosis in senescent cells." (PMID 39857806, 2025). "It focuses on how the dysregulation of Bcl-2 and Bcl-xL affects pancreatic β-cell function and survival, and the consequences for diabetes development." (PMID 39857806, 2025). "The increase in Bax and decrease in Bcl-2 levels in diabetes create a pro-apoptotic environment, leading to higher rates of cell death." (PMID 40184394, 2025). "The upregulation of BAX and cleaved caspase-3 and the downregulation of BCL2 expression in db/db mice indicated increased apoptosis resulting from diabetes." (PMID 38200543, 2024). "In summary, BCL2 is reduced in various target organs affected by diabetes, accelerating apoptosis of the corresponding cells and exacerbating diabetes‐related damage." (PMID 39730319, 2024). "Many studies have shown that Bax, a proapoptotic factor, is upregulated in the heart after diabetes, whereas Bcl2, an antiapoptotic factor, is downregulated." (PMID 38532054, 2024). "In cases of erectile dysfunction in individuals with diabetes, caspase-3 and Bax are upregulated and Bcl-2 is downregulated in the tissue of the corpus cavernosum in rats." (PMID 38990890, 2024). "In this study, the downregulation of renal expression of Bcl-2 in STZ-induced diabetic rats induced diabetic nephropathy." (PMID 38640098, 2024). "GLX7013170 reversed the diabetes effect on Bcl-2 levels, suggesting a role for the NOX2 isoform in the regulation of apoptosis in ESDR, in agreement with other studies." (PMID 38543179, 2024). "The survival of neuronal cells was compromised by diabetes, as reflected in the reduction of Bcl-2 levels (438.7 ± 9.150, p < 0.05) in T2DM rats, compared to control rats (662.9 ± 42.67)." (PMID 39766390, 2024). "Studies have indicated that as diabetes progresses, there is a decline in the expression of Bcl-2 and a rise in the expression of Bax, resulting in the activation of caspase-3 and the initiation of cellular apoptosis." (PMID 38990890, 2024). "In the seminal vesicles of rats with diabetes mellitus, quercetin was reported to exert a strong anti-apoptotic effect by reducing the expression of cleaved-caspase 3 and helping to increase the BCl-2/BAX ratio." (PMID 38542468, 2024). "In the Dia + CM group, expression level of Bcl-2 mRNA was significantly increased compared to the diabetes group (P < 0.05)." (PMID 37081849, 2023). "Our research found that the Bax/Bcl2 ratio in the crocin-treated and regular exercise groups was significantly lower than in the control diabetes group." (PMID 38113243, 2023). "Treatment of diabetic rats with GYY4137 attenuated thermal hypoalgesia and prevented both the diabetes-induced increase in Bax mRNA expression (p = 0.0032) and the diabetes-induced decrease in Bcl2 mRNA expression (p = 0.028)." (PMID 38068971, 2023). "Our findings showed that the Bax/Bcl-2 ratio was significantly higher in the control diabetes group than in the sham group." (PMID 38113243, 2023). "BCA treatment improved Bcl-2 level and attenuated Bax and cleaved caspase-3 expression in diabetic kidneys and HG-induced NRK-52E cells." (PMID 37237918, 2023).
diabetes (continued). "Herein, the presence of periodontitis and diabetes alone and in combination significantly decreased the expression of Bcl-2 and induced that of Bax." (PMID 37396943, 2023). "Studies have shown that diabetes increases oxidative stress, induces apoptosis in heart tissue, and increases Bax and decreases Bcl-2 expression." (PMID 38113243, 2023). "In a model of diabetes-related neurodegenerative disease, Dapa exerted anti-apoptotic and anti-inflammatory effects by regaining normal levels of bax, bcl-2, and phosphorylated NFκB p65 expression in HFD-induced obese rats." (PMID 38255143, 2023). "On the other hand, the mRNA expression level of Bcl-2 in the diabetes group was significantly lower than in the control group (P < 0.01)." (PMID 37081849, 2023). "It has been indicated that diabetes induces neuronal apoptosis by downregulating antiapoptotic Bcl-2 expression and upregulating the proapoptotic Bax gene." (PMID 37081849, 2023). "Using eight weeks of continuous exercise and administration of crocin significantly reduced blood sugar levels and lipid peroxidation and increased the activity of antioxidant enzymes and Bcl-2 gene expression compared to the diabetes control group." (PMID 38113243, 2023). "NQO1 overexpression notably inhibited diabetes-induced Cleaved Caspase-3 expression and reversed the ratio of Bax to Bcl-2 in kidneys." (PMID 35090502, 2022). "For example, the coding genes VEGFA, HGF1R, and BCL2, which exhibiting higher degree and BC in the network, have been found to be involved in diabetes and DR progression." (PMID 34707685, 2021). "For example, the coding genes VEGFA, HGF1R, and BCL2 have been found to be involved in diabetes and DR progression." (PMID 34707685, 2021). "The levels of apoptosis-related proteins, such as Caspase-3 and Bax, were increased due to diabetes, and the level of the antiapoptotic protein Bcl-2 was decreased." (PMID 34395424, 2021). "Based on the collected data, the expressions of apoptosis-related proteins, including Bcl2, Bax, and cleaved caspase-3, are presented graphically, demonstrating that apoptosis was increased in diabetes and remarkably decreased following GS-E3D administration." (PMID 33445772, 2021). "The rhGH treatment decreased the expression of the proapoptotic proteins BAX and cleaved caspase-3 and increased the expression of the antiapoptotic protein Bcl-2 in mice with diabetes." (PMID 34925693, 2021). "The antiapoptotic protein BCL2 was significantly decreased in the knee joint cartilage of diabetic OA rats (p < 0.01)." (PMID 33468174, 2021). "We determined the effect of STZ-induced diabetes and myocardial IR on cardiac Bcl-2 expression by Western blotting and immunohistochemistry." (PMID 32751309, 2020). "At the end of the experiment, ZDF rats treated with RLE showed a reduction of the diabetes-associated up-regulation of both NOX4 and the p47-phox and p22-phox subunits, and restored the BAX/BCL-2 ratio respect to ZDF rats." (PMID 32466228, 2020). "In diabetes, an increased expression of pro-apoptotic genes, including an increased Bax/Bcl-2 ratio, was reported, which corresponds with increasing of apoptosis." (PMID 32615920, 2020). "We further found that Bcl-2 expression was higher in the liraglutide-treated group than in the diabetes group and that miR-34a-5p and Bcl-2 expression levels were negatively correlated." (PMID 30863684, 2019). "Apoptosis, which is jointly regulated by the apoptosis-inducing gene Bax and the apoptosis-inhibiting gene Bcl-2, is considered a major factor in the possible mechanism of testicular injury induced by diabetes." (PMID 31871550, 2019). "The representative Western blot results demonstrated that diabetes with cardiac I/R injury increased the expressions of BimEL and Bax and decreased the levels of Bcl-2." (PMID 29576852, 2018). "In parallel, ZP2495 increased levels of the antiapoptotic proteins Bad and Bcl-2, which alleviated the apoptosis induced by diabetes and cardiac I/R injury." (PMID 29576852, 2018).
diabetes (continued). "It has been proposed that apoptosis occurs in diabetes due to increase in the expression of Bax proapoptotic gene and decrease the expression of Bcl-2 and Bcl-XL antiapoptotic genes as well as increasing caspase 3 activity." (PMID 30597853, 2018). "In the diabetes + IR rat hearts, there was increased expression of pro-apoptotic proteins (Bax and Caspase-3) and decreased expression of anti-apoptotic protein Bcl-2." (PMID 28181586, 2017). "NAC significantly attenuated the increase in the ratio of Bax/Bcl-2 and prevented diabetes and I/RI-induced increase in cleaved-caspase-3 expression (all p < 0.05)." (PMID 28265179, 2017). "Diabetes alone mostly induced apoptotic cell death via activated Bax andCaspase-3 proteins, and suppressed Bcl-2 activity." (PMID 29160389, 2017). "Diabetes significantly increased myocardial caspase-3 activity (P <0.01) and the ratio of Bax/Bcl-2 (P < 0.05 or P < 0.01)." (PMID 26623724, 2016). "Inhibited phosphorylation of AMPK was restored and the interaction between Bcl-2 and Beclin1 was enhanced in diabetes + trimetazidine group, resulting in the initiation of autophagy and alleviation of apoptosis." (PMID 27121077, 2016). "In the rapamycin treatment group, Bcl2 expression was increased in relation to the diabetes + SCI group, whereas the expressions of both C-caspase 3 and Bax declined, indicating that over-activation of autophagy inhibited the rate of apoptosis in diabetic SCI." (PMID 26597839, 2015). "We further investigated the scheme of events involved in diabetes-induced stress, which included changes in apoptotic genes like Bax, and antiapoptotic gene Bcl-2." (PMID 28962270, 2014). "The significant increase in the expression of Bcl-2 in diabetic rats compared with control non diabetic rats was to counteract the oxidative stress arisen by diabetes." (PMID 24364912, 2013). "Analysis of Bax/Bcl-2 ratio as one of mitochondrial cell death pathway disclosed a synergistic increase in Bax/Bcl-2 ratio in the liver of Diabetes/TPEN as compared to Diabetes and TPEN alone." (PMID 23251339, 2012). "There is also clinical support for this concept, since insulin-dependent diabetes mellitus (IDDM) patients show significantly reduced Bcl-2 expression in CD3+ and memory CD4+CD45RO+ populations and have higher levels of spontaneous apoptosis." (PMID 18773086, 2008). "Likewise, diabetes induced testicular apoptosis, demonstrated by increased Bax and caspase-3 levels and decreased Bcl-2 levels." (PMID 41683695, 2026). "In the context of ED, BCL2 may act by affecting the apoptotic process in penile cavernous tissue, especially in diabetes‐related ED, and BCL2 may protect cavernous tissue through its anti‐apoptotic effects." (PMID 40443781, 2025). "This mechanistic explanation aligns with recent studies demonstrating that carotenoid-rich and antioxidant extracts can suppress apoptosis through regulation of Bcl-2/Bax expression and attenuation of ROS-mediated damage in diabetic retina models (see updated references." (PMID 41302178, 2025). "Bcl-2 can also be regulated by Bag-1, an anti-cell death protein that binds to and upregulates Bcl-2 activity in hippocampal neurons and cardiomyocytes in the context of diabetes." (PMID 39857806, 2025). "Altogether, these findings suggest that targeting Bcl-2 and Bcl-xL could represent a viable strategy to mitigate β-cell dysfunction and death, contributing to advancements in diabetes treatment." (PMID 39857806, 2025). "Previous research has demonstrated reduced Bcl2 expression in response to diabetes stimuli." (PMID 38726423, 2024). "Additionally, the testicular Bax/Bcl-2 ratio was significantly higher (P < 0.01) in the diabetes group compared to the control group." (PMID 39391856, 2024). "In addition, IL-17 can also inhibit the transcription of anti-apoptotic gene BCL-2 mRNA and accelerate the apoptosis of islet cells, which is closely related to the onset of diabetes." (PMID 38470866, 2024).
diabetes (continued). "Understanding the control of Bcl‐2 expression in response to diabetic stimuli could offer a valuable understanding of the development and progression of diabetes‐related complications." (PMID 38726423, 2024). "However, the Bcl-2 mRNA and protein levels in the diabetic groups treated with crocin and regular exercise increased compared to the diabetes group." (PMID 38113243, 2023). "Several studies showed that Bcl-2 and Bax’s genes strongly link diabetes, CNS, and neuropathy." (PMID 38068971, 2023). "Western blot results showed that the expression level of Bcl-2 in the diabetes + 400 mg/k T. vulgaris group (0.334 ± 0.104) was significantly higher than that in diabetes group (0.08 ± 0.018) (P < 0.0001); expression level of Bax protein in the diabetes + 400 T." (PMID 35368767, 2022). "This is expected as poor glycemic control represses the expression of Bcl2 in diabetes." (PMID 33562428, 2021). "The induction of diabetes altered Bcl2 expressions in the untreated diabetic kidneys." (PMID 33562428, 2021). "The protein levels of BCL-2, caspase-9, and caspase-8 were also assessed to examine whether diabetes induces apoptosis in the cochlea." (PMID 34445504, 2021). "The BAX/BCL2 expression ratio in DM-iD was also significantly higher than in DM-pD (5.0-fold vs 0.6-fold, p=0.003), suggesting higher cellular apoptotic rate only in cases of diabetes with impaired osteogenic differentiation ability." (PMID 34512554, 2021). "Diabetes significantly decreased Bcl-2 expression and enhanced Bax expression in the hippocampus." (PMID 32766246, 2020). "We explored whether diabetes diminished BAG3/Bcl-2/Nrf-2/HO-1-mediated cardioprotection and overproduced oxidative stress contributing to exaggerated IR injury." (PMID 32751309, 2020). "However, Met reduced the diabetes-induced increases in cardiomyocyte apoptosis and the Bax/Bcl-2 ratio." (PMID 32508669, 2020). "Furthermore, FGF1 administration significantly blocked diabetes-induced decrease of Bcl-2 expression and increase of Bax expression, subsequently upregulated Cleaved-Caspase3 expression (p < 0.05)." (PMID 32460803, 2020). "Although miR-29a and miRNA-29c might target the BCL2-modifying factor to regulate apoptosis levels induced by HG in the LECs of diabetic rats, the contributions of miRNAs to the human diabetic cataract pathogenesis are not clearly understood." (PMID 29100392, 2017). "Diabetes was also associated with increased postischemic apoptotic cell death manifested as increases in TUNEL positive cells, cleaved-caspase-3, and ratio of Bax/Bcl-2 protein expression." (PMID 28265179, 2017). "Similarly, in this present study, there was increased expression of JNK, p38, Bax and decreased expression of ERK1/2 and Bcl-2 in the diabetes + IR group while an opposite effect was seen in the mangiferin treatment group." (PMID 28181586, 2017). "Studies showed that APS could enhance the expression of Bcl-2, reduce the expression of caspase 3 and apoptosis of islet cells in type 1 diabetes mellitus." (PMID 28610566, 2017). "TFF attenuated diabetes-induced apoptosis in retinal neurons by inhibiting Bax expression and increasing the ratio of Bcl-2 to Bax, which suggests that TFF might prevent retinal neuronal damage in diabetes mellitus." (PMID 24146535, 2013). "Linking the modulation of ASK1 and Bcl-2 levels in hyperglycemia, ER stress response might play a critical role in endothelial cell dysfunction in diabetes." (PMID 22474423, 2012).
diabetes (continued). "Recent evidence, however, shows the ability of Bcl-2 and Bcl-xL to protect human β-cells without impairing insulin release, introducing a promising avenue for β-cell-specific therapies aimed at preventing β-cell loss during diabetes progression." (PMID 39857806, 2025). "Previous studies indicate that diabetes during pregnancy may elevate pro‐apoptotic gene expression (Bax) while reducing anti‐apoptotic gene expression (Bcl‐2) in the hippocampus, potentially resulting in increased neural tissue damage and impairing neurodevelopmental processes." (PMID 40660790, 2025). "We discovered diabetes triggered cardiomyocytes apoptosis and increased Bax/Bcl-2 ratios in DM mice compared with control mice." (PMID 32508669, 2020). "In our study, we found out that the Bax mRNA expression was higher in the DM-S group, while Bcl-2 mRNA expression was similar between DM-S and S groups, and the Bcl-2/Bax ratio was lower in the DM-S group, suggesting that cell apoptosis was induced by diabetes." (PMID 30402501, 2018). "Furthermore, the combined therapy applied here of MSCs and PIO reduced apoptosis in the heart in diabetes as evident by lowering levels of pro-apoptotic markers i.e. caspase-3, cleaved caspase-3 and Bax and increasing the levels of anti-apoptotic marker, Bcl-2 in the heart of diabetic rats." (PMID 29959408, 2018). "Bcl-2 is known to be reduced in high glucose-exposed endothelial cells which may lead to the increase in intracellular AGE (characteristic of endothelial cell dysfunction in diabetes levels)." (PMID 22474423, 2012). "Compared with the diabetes group, P. copri HF2123, HF1478, and HF2130 treatment significantly decreased caspase-3 protein and increased bcl-2 protein levels in pancreatic tissues of db/db mice." (PMID 38934548, 2024). "Compared to control group, the protein expression of TRPM2, bax, cleaved caspase-3, and P62 was significantly elevated, and the protein expression of bcl-2 and LC3-II was significantly decreased in the myocardial tissues of the HFD/STZ-induced diabetes group." (PMID 38308007, 2024). "Consistent with our finding, previous studies indicated that HIIT reduced apoptosis via increasing Bcl2 and decreasing BAX expression in heart following diabetes." (PMID 38233819, 2024). "The identification of FOXD1 as a critical transcription factor for BCL-2 in the retina and kidney and the TRIM21-mediated regulation of FOXD1 stability complement our findings regarding therapeutic strategies for diabetes mellitus." (PMID 38092733, 2023). "Diabetes impairs AMPK activation of MAPK8/JNK1/BCL2 signalling and subsequent BECN1-BCL2 dissociation, promoting apoptosis by suppressing autophagy." (PMID 36267813, 2022). "Western blot analysis showed that the Bax/Bcl‐2 ratio and cleaved caspase‐3 expression were significantly increased in the Sur group and DM group compared with the control group on postoperative days 3 and 7 and were further increased in surgery‐treated rats with diabetes (p < 0.05)." (PMID 34784444, 2022). "This adipokine also decreased the apoptosis of myocardial cells in rats via bcl-2 and reduced the apoptosis of beta cells at physiological concentrations in vitro by maintaining or up-regulating bcl-2 expression, which could promote non-insulin-dependent diabetes mellitus." (PMID 36555171, 2022). "The present study showed that CNPs treatment suppresses diabetes-induced apoptosis in the testicular tissue by reducing the proapoptotic BAX gene expression and enhancing antiapoptotic Bcl-2 gene expression along with the downregulation of BAX/Bcl-2 ratio." (PMID 34458667, 2021). "Our present data evidenced that diabetes decreased BAG3, Bcl-2, Nrf-2 and HO-1 expression, further reduced myocardial IR-depressed BAG3, Bcl-2, Nrf-2 and HO-1 expression and increased cleavage caspase 3/PARP, leading to apoptosis formation in the heart." (PMID 32751309, 2020).